MUC2 (mucin 2, oligomeric mucus/gel-forming)
Diseases named in the same sentence as MUC2 in open-access papers (continued):
Sharing a sentence is not in itself a finding about the gene and the disease.
tumor (continued). "Confirmatory immunostaining with appropriate controls performed on this case revealed that the tumor cells are positive for CDX2 and MUC2 (focal) but negative for CK5/6, S100, p16, and GCDFP15." (PMID 40438862, 2025). "On immunohistochemical analysis, the tumor was positive for MUC5AC and MUC6 and negative for MUC2 and CDX2, indicating a gastric phenotype." (PMID 41256328, 2025). "Since MUC2 expression was impaired in healthy GPR120 ΔIEC mice —but not in tumor bearing mice —we analyzed the protein composition of the mucus layer." (PMID 35013389, 2022). "In contrast, MUC2 for goblet cells was negative, and MUC5AC for foveolar cells was stained in the non-atypical foveolar epithelium that was covered on the tumor surface." (PMID 35029193, 2022). "Immunohistochemically, the tumor cells were positive for MUC6 and MUC5AC and negative for intestinal-type markers such as MUC2, CD10 and CDX2." (PMID 34160413, 2021). "Intraductal pancreatic mucinous neoplasm (IPMN) often shows positivity for MUC5 and MUC6 in the gastric and pancreaticobiliary types and positivity for MUC2 and MUC5 in the intestinal type, but these markers were all negative in this tumor." (PMID 34940081, 2021). "In concurrence with this notion, HLA peptide ligands from MUC2 and DACH1 were reliably detected from all the CRC tumor clones analyzed, whereas we did not detect the proteins in the quantitative proteomics screen." (PMID 33087703, 2020). "Tumor cells were strongly and diffusely positive for CK7, CK19, MUC1 and negative for CK20, CDX‐2, MUC2." (PMID 31102323, 2019). "MUC2 expression was more frequently found in N-cadherin-negative CCs, while the expression of MUC1 was similar in both groups of tumours." (PMID 30875782, 2019). "Immunohistochemical analysis showed positive staining for pepsinogen I, H+/K+-adenosine triphosphatase, MUC6, and MUC5AC and negative staining for MUC2 and CD10, indicating tumor differentiation into fundic gland mucosa." (PMID 30212986, 2018). "Immunohistochemical analysis revealed that these tumor cells tested positive for CK7, CK20 (weakly), MUC5AC, MUC6, CDX2 (patchy), CEA, and CA19-9 and negative for MUC2, ER, and PgR." (PMID 25386374, 2014). "Immunohistochemical analysis (IHC) revealed that those tumor cells tested positive for CK7, CK20 (weakly), MUC5AC, CEA, and CA19-9 and negative for MUC2, MUC6, and CDX2." (PMID 25386374, 2014). "In our case the tumor was positive for CEA, CK 7 and TTF-1 and negative for CK 20, ER, COX2, CK 14, CDX2, and MUC2." (PMID 24716057, 2014). "In this report, tumor cells showed positive reaction for E-ca, CDX2 and MUC1, and negative reaction for MUC2, Hep Par1 and TTF-1." (PMID 23938020, 2013). "CTSE expression of non-cancerous gastric mucosa adjacent to tumor lesion was evaluated, together with MUC5AC and MUC2." (PMID 23451082, 2013). "The lack of MUC2, MUC5B, superficial MUC6 and sialylation of non-tumor samples confirms the pathologist's report stating that these specimens were normal." (PMID 22563496, 2012). "The survival rates were not significantly different when patients had or had no expression of MUC1, MUC2, MUC5AC, or MUC6 in tumor." (PMID 22027009, 2011). "Essentially all the tumor cells demonstrated strong cytoplasmic MUC1 staining, but were negative for MUC2, MUC4, MUC5AC and MUC6." (PMID 20550696, 2010). "The tumor cells showed ductal-like cytoplasmic MUC1 staining, but were negative for MUC2 and other mucin gene markers." (PMID 20550696, 2010). "No appreciable expression of MUC2 and MUC5AC in normal and tumor tissues was detected by slot blot analyses." (PMID 16188033, 2005). "In the present study, the incidences of MUC2-negative tumours and CD10-positive tumours were significantly higher in the haematogenous recurrence group than in the control group." (PMID 15354218, 2004). "The anti-MUC2 and anti-MUC5AC antibodies stained the cytoplasm of very few tumour cells in the compact areas (data not shown)." (PMID 14760390, 2004).
tumor (continued). "In contrast, the perihilar tumor exhibited positive for MUC1 and MUC5AC, but negative for MUC2." (PMID 37721561, 2023). "Immunohistochemically, tumor cells were positive for Vimentin (mesenchyme), CK7, CK19, MUC-1, MUC-5AC, MUC-6, S-100p (focal), Ki-67 (12%), and negative for Inhibin-α, ER, CK20, CEA, and MUC-2." (PMID 33592896, 2021). "The mucin markers MUC5AC, MUC6, MUC2 and CD10 were considered necessary, although there is no consensus on the number of markers that should be used to define a mucin phenotype or the percentage of tumour cells that must be stained." (PMID 34256780, 2021). "However, the tumor in the present case was classified as invasive IPMC, despite the negative MUC2 expression." (PMID 33815792, 2021). "This also showed cytoplasmic or membranous expression of MUC-1, (Abcam, Ab696-250, 1:100) predominantly in the deeper aspect of the tumour, but did not stain for MUC-2 (Novocastra, NCL MUC2, 1:100), MUC5 (Novocastra, NCL MUC5, 1:100) or MUC-6 (Novocastra, NCL MUC6, 1:100)." (PMID 26589730, 2015). "The tumor cells were diffusely positive for CK7 and MUC1 and negative for MUC2 and HER2-neu." (PMID 24367734, 2013).
infection (156 papers, 2010 to 2026). The state of being infected such as from the introduction of a foreign agent such as serum, vaccine, antigenic substance or organism. "RV infection of Muc2 knockout mice recapitulated the secretory cell deletion phenotype, indicating that goblet cell loss is responsible for attenuated infection." (PMID 39727412, 2025). "Immunostaining of Muc2 also showed a reduction at 8 dpi (0.14 ± 0.10x106 pixels), consistent with loss of mucosal barrier function at the peak of infection, before partial recovery at 13 dpi." (PMID 40630939, 2025). "Another report also revealed that LI infection of intestinal crypt cells was associated with specific depletion of secreted Muc2 in goblet cells." (PMID 37372164, 2023). "An association between mucus hyperproduction and infection by the genus Pseudomonas has been described, as well as a direct relationship between the overexpression of MUC-2 and MUC-5AC and the lipopolysaccharides of this bacterial family." (PMID 37373701, 2023). "Upregulating the genes encoding for TJ protein before infection and MUC-2 after infection indicated the protective effects of GE against C. jejuni colonization." (PMID 33415133, 2020). "In resistant mice, IL-13 also induces goblet cell hyperplasia and elevated Muc2 and Muc5ac mucins, with deficiency of these mucins causing susceptibility to infection." (PMID 31730667, 2019). "Loss of the mucus layer in MUC2-deficient mice has been shown to increase the susceptibility to lethal infection induced by pathogenic and commensal flora." (PMID 27548209, 2016). "Around the time of expulsion, there was a remarkable increase in Muc5ac expression in Muc2 deficient mice triggered by the infection." (PMID 25436881, 2013). "In cattle, an infection with the intestinal nematode Cooperia oncophora also altered the mucus composition, causing induction of MUC2 and a downregulation of MUC5B in the small intestine." (PMID 21569362, 2011). "These animals exhibited a significant delay in worm expulsion even though the adaptive immune response was unaltered; similar TH2-type immune responses were shown in Muc2-deficient and WT control mice after infection." (PMID 20138044, 2010). "Analysis of cecal mucus from Muc2-deficient mice showed that Muc5ac was the only polymeric mucin present in the mucus after infection." (PMID 20138044, 2010). "Meanwhile, gene expression analysis revealed that in the ΔsaaS group, Muc1 (encoding Mucin-1) had higher expression at 6 hpi; Muc2 (encoding Mucin-2) had higher expression throughout infection; while Muc4 (encoding Mucin-4) had higher expression at 72 hpi and 120 hpi." (PMID 37158502, 2023). "The maintenance of Muc2 mRNA expression is important, since the mucus layer acts as an important barrier protecting gut epithelial cells from damage and infection by pathogenic bacteria and reduced Muc2 mRNA has been associated with several gastrointestinal diseases." (PMID 33494480, 2021). "Muc2 is also associated with resistance in T. muris models of infection." (PMID 31730667, 2019). "However, in the chronic models of infection, there was a decrease in Muc2 expression, accompanied by a loss of sulphated goblet cell thecae and an increase in sialomucins within the goblet cells." (PMID 28192541, 2017). "Tracheal mRNA levels of Muc5ac and Muc2 were significantly increased 12 hours after infection in mCLCA3-deficient mice and wild-type mice compared to PBS controls, whereas 24 hours after infection only Muc5ac was slightly elevated in the trachea of infected animals." (PMID 25033194, 2014). "Therefore, to further understand the role of Muc2 in T muris infection, we performed a high-dose infection in Muc2-deficient mice on the resistant C57BL/6 background." (PMID 20138044, 2010).
infection (continued). "Although a marked impairment in the development of periodic acid Schiff (PAS)–stained intestinal goblet cells was observed in Muc2-deficient mice, as infection progressed a significant increase in the number of PAS-positive goblet cells was observed in these mice." (PMID 20138044, 2010). "To investigate whether MUC2, the predominant mucin produced by intestinal goblet cells, influenced susceptibility to RV infection, we infected Muc2-/- mice (Muc2KO) and WT littermate controls with RV and examined goblet cell morphology and infection kinetics." (PMID 39727412, 2025). "Within 4 h of infection with a commensal or pathogenic E. coli O157:H7 strain, upregulation of the transcription of proteins that participate in gastrointestinal defenses was seen, including the mucins (MUC2 and MUC13), the structural component of gastric mucus; trefoil factor." (PMID 32636253, 2020). "Resistant (BALB/c, C57BL/6), susceptible (AKR), and Muc2-deficient mouse strains were infected with the nematode, Trichuris muris, and worm expulsion, energy status of the whipworms, changes in mucus/mucins, and inflammatory and immune responses were investigated after infection." (PMID 20138044, 2010). "The downregulation of MUC2 during infection is driven by parasite-induced epithelial stress, pro-inflammatory cytokines (as TNF-α and IFN-γ), and oxidative damage, which impair goblet cell function and mucin gene transcription." (PMID 41479898, 2025). "At the peak of the infection, significant tissue damage and inflammation take place, and the integrity of the Muc2 layer is compromised due to the depletion of goblet cells." (PMID 40630939, 2025). "We confirm this using a novel transgenic mouse model exclusively expressing human MUC2, which allows us to study the role of the mucus layer in the infection by human intestinal pathogens." (PMID 41476084, 2025). "After infection, tissues were stained for MUC2 and Jacalin to visualize the mucus layer and DAPI to visualize both bacteria and epithelial nuclei." (PMID 39714032, 2025). "The secretory mucin MUC2 and immunological components play important roles in the anti-infection of the intestinal barrier." (PMID 40616183, 2025). "Here, we demonstrate the mechanism by which EatA degrades the core mucus component MUC2, thereby facilitating access to the epithelial cell surface and promoting infection." (PMID 41476084, 2025). "By 24 hours, MUC2 expression increased slightly, possibly reflecting a secondary response to ongoing infection." (PMID 41278481, 2025). "Our study shows that during the acute phase of diarrhea (3 days post-infection), animals in the RV group displayed lower MUC2 gene expression and number of goblet cells per villus in jejunum samples compared to the CON group." (PMID 38256253, 2024). "A concomitant infection-induced increase in Muc2 levels in the distal colon lumen was also observed by dot blot." (PMID 39428744, 2024). "This layer has been previously shown to arise solely from goblet cells in the proximal colon, indicating that in response to infection, these cells increase their release of Muc2 which subsequently migrates down to the distal colon." (PMID 39428744, 2024). "On the day 1 of infection, the mRNA transcript levels of tight junction proteins (Claudin-1 and Occludin) and mucin (MUC-2) were significantly reduced in the jejunum and ileum of chicks in the SP group compared to the NC group." (PMID 38863452, 2024). "In response to infection, goblet cells release MUC2 and other proteins, enhancing the mucus barrier as a mechanism to trap virus particles." (PMID 38256253, 2024). "Luminal content from the ceca of IL-18 treated Il22−/− mice contained greater amounts of Muc2 protein after infection, suggesting local goblet cells released more Muc2 in response to IL-18 treatment." (PMID 39428744, 2024).
infection (continued). "The results demonstrated down-regulation in the transcription and expression of the MUC–2 protein and the tight-junction proteins of occludin and ZO–1 upon PAstV–4 infection." (PMID 38891045, 2024). "Crucially, our data indicate that local resistance to infection is mediated by the presence of a Muc2-dependent microbiota that provides colonization resistance against the pathogen." (PMID 36753416, 2023). "In this study, the expression of Muc2 gene in mouse ileum was downregulated after infection with C. perfringens type C and increased after treatment with engramycin or probiotics." (PMID 37138630, 2023). "For example, increased production of MUC2 during an RVA infection has also been found to be one of defence mechanisms in germ-free (GF) mice, while changes in glycosylation profiles of the intestinal mucins were observed in the course of RVA infection of mice." (PMID 37848925, 2023). "In the small intestine, meprin β is responsible for cleavage and detachment of the major mucus component mucin-2 (MUC2), thereby preventing bacterial overgrowth and infection." (PMID 37000885, 2023). "The amount of goblet cells and MUC2 gene expression were used as apoptotic indicators, and both were considerably downregulated by infection." (PMID 36875142, 2023). "As shown by the gene expression results, the BCoV-infected enteroids in our study (at least P3 at the time of infection) showed the downregulation of Muc2 at 72 hpi." (PMID 36992344, 2023). "It was reported that MUC-2 exerted a major role in protecting the intestinal epithelium in preventing infection and maintaining the integrity of the intestinal mucosal barrier." (PMID 36937262, 2023). "When ERdj5-KO mice were exposed to environmental insults, such as DSS, TLR ligands, and infection, MUC2 production and goblet cells were markedly decreased in the colons of ERdj5-KO mice." (PMID 36759578, 2023). "Before experimental infection (60 d of age), the expression levels of MUC-2 and JAM-2 were prominently upregulated (p < 0.05) in groups fed MSP at a level of 1 × 108 CFU/kg when compared with the control group (1.73- and 1.44-fold, respectively)." (PMID 36009671, 2022). "Under pathological and mucosal inflammatory conditions, infection leads to a decrease in mucus production and MUC2 protein expression, which directly affects the morphological and functional activity of GCs." (PMID 36012293, 2022). "An in vivo ETEC F18 challenged study observed that ETEC-infected pigs expressed more MUC2 gene in the jejunal mucosa during the peak of infection." (PMID 35990617, 2022). "MUC1 has been demonstrated to play a dynamic role in protection of the host from infection by a wide variety of pathogens and to regulate inflammatory responses to infection, while MUC2 has been shown to be important in the establishment of the mucus layer." (PMID 36676016, 2022). "Firstly, we confirmed that C. jejuni NCTC 11168 infection induced an altered transcription of MUC2 and the co-secreted peptide TFF3 in human intestinal epithelial cells in vitro." (PMID 34183045, 2021). "An inverse correlation between two predicted miRNAs and MUC2 as well as TFF3 was observed in the early phase of C. jejuni NCTC 11168 infection in human cells." (PMID 34183045, 2021). "In colonic tissue samples, we confirmed infection-dependent aberrant transcription of MUC2 and TFF3." (PMID 34183045, 2021). "Based on our analysis, anti-correlated expression of miR-125a-5p and miR-615-3p was associated with the dysregulation of MUC2 and TFF3 transcription at the early stage of C. jejuni NCTC 11168 infection in vitro." (PMID 34183045, 2021). "To test if the antibiotic-induced death of Muc2−/− mice resulted from the presence of the protozoan infection, we performed an experiment using Muc2−/− mice free of infections (including Tsp), Muc2+/+ littermates were used as a control." (PMID 34639039, 2021).